OR2H2 (olfactory receptor family 2 subfamily H member 2)
Description:
Odorant receptor.
Synonyms: FAT11; OLFR2; OR2H3; hs6M1-12; OLFR42B; dJ271M21.2
Tractability: Small molecule: it belongs to a druggable protein family. Antibody: UniProt places it where antibodies can reach, with medium confidence; UniProt predicts a signal peptide or a membrane-spanning region; its Gene Ontology location is reachable by antibodies, with medium confidence.
Gene: Protein-coding gene on chromosome 6 (29,585,121 to 29,590,500, forward strand). Ensembl gene ENSG00000204657.
Subcellular location: Cell membrane
Pathways (Reactome):
Sensory Perception: Expression and translocation of olfactory receptors
Gene Ontology:
Molecular function: olfactory receptor activity; G protein-coupled receptor activity
Biological process: defense response; detection of chemical stimulus involved in sensory perception of smell; mating; G protein-coupled receptor signaling pathway
Cellular component: plasma membrane; membrane
Genetic constraint (gnomAD): Missense variants: 47 observed, 52.73 expected, observed/expected ratio (o/e) 0.89, 90% interval 0.7 to 1.14. Synonymous variants: 18 observed, 21.16 expected, observed/expected ratio (o/e) 0.85, 90% interval 0.59 to 1.26.
Homologues: Orthologues: macaque OR2H2 (95% identical), dog OR2H10 (59% identical). Paralogues in human: OR2H1 (87% identical), OR2C1 (59% identical), OR2G3 (59% identical), OR2G2 (56% identical), OR2W3 (56% identical), OR2B11 (56% identical), OR2G6 (56% identical), OR2J1 (56% identical), OR2J2 (56% identical), OR2J3 (56% identical), OR2B2 (56% identical), OR2B6 (55% identical), and 80 more.
Diseases named in the same sentence as OR2H2 in open-access papers:
OR2H2 is named in the same sentence as 14 diseases in open-access papers, as found by Europe PMC text mining. Sharing a sentence is not in itself a finding about the gene and the disease. The quoted sentences say what the papers report.
celiac disease (1 paper, 2023). An autoimmune genetic disorder with an unknown pattern of inheritance that primarily affects the digestive tract. "The single nucleotide polymorphism of OR2H2, rs123388, is linked to celiac disease in patients from Indian and Dutch populations." (PMID 37765029, 2023).
follicular thyroid carcinoma (1 paper, 2021). "The expression of OR2H2 was only reduced in follicular thyroid carcinoma tissue." (PMID 34385931, 2021). "In vitro characterization confirmed that ligand OR2H2 and OR2W3 interaction has a functional impact on cancer biology, increasing the invasive potential of follicular thyroid cancer cells." (PMID 34385931, 2021).
thyroid cancer (1 paper, 2021). "In sum, we demonstrate that ORs such as OR2H2 and OR2W3 are not only expressed in healthy human thyroid tissue but also human thyroid cancer cells and respond to their ligands via a combination of cAMP and IP3 dependent signaling." (PMID 34385931, 2021).
cancer (1 paper, 2021). A tumor composed of atypical neoplastic, often pleomorphic cells that invade other tissues. "Both ORs were detectable in human thyroid tissues with significantly higher mRNA expression in healthy surrounding thyroid tissue than in carcinoma tissues with the exception that the expression of OR2H2 mRNA in PTC remained unchanged." (PMID 34385931, 2021).
OR2H2 also shares sentences with these, for which no sentence is quoted: atherosclerosis (9 papers); aneurysm (1); aortic atherosclerosis (1); breast carcinoma (1); chronic graft versus host disease (1); Graves disease (1); lung adenocarcinoma (1); lung carcinoma (1); mumps (1); thyroid (1).